MIR550A3 (microRNA 550a-3)
Synonyms: hsa-mir-550a-3; mir-550a-3
Gene: MicroRNA gene on chromosome 7 (29,680,734 to 29,680,828, reverse strand). Ensembl gene ENSG00000212024.
Gene Ontology:
Biological process: miRNA-mediated post-transcriptional gene silencing
Cellular component: RISC complex